CRP (C-reactive protein)
Diseases named in the same sentence as CRP in open-access papers (continued):
Sharing a sentence is not in itself a finding about the gene and the disease.
lymphopenia (continued). "Clinically, the hallmarks of hyperinflammation include high serum levels of C-reactive protein (CRP), reduction or absence of lymphocytes (lymphopenia), high levels of ferritin and D-dimer, increased lactate dehydrogenase and higher neutrophil-to-lymphocyte ratio (KE1868)." (PMID 35956081, 2022). "In the acute stage of disease, markers of inflammation such as C-reactive protein (CRP), ferritin, lactate dehydrogenase, and coagulopathy such as prothrombin times, D-dimer were reported to be elevated in most patients in addition to thrombocytopenia and lymphopenia." (PMID 34820400, 2021). "In one case, a detailed laboratory investigation revealed lymphopenia and elevated aspartate aminotransferase (AST), alanine aminotransferase (ALT), c-reactive protein (CRP), and lactate dehydrogenase (LDH), which may be associated with greater illness severity." (PMID 32656006, 2020). "These include markers of inflammation (elevated C-reactive protein (CRP)), cytotoxicity (increased lactate dehydrogenase (LDH)), and both macrovascular and microvascular thrombosis in systemic and pulmonary circulations (higher D-dimer levels), as well as lymphopenia." (PMID 33291238, 2020). "Standard laboratory tests were all within normal limits, C-reactive protein level (0.5 mg/L; normal level, < 5 mg/L) and Ferritin level (246.4 ng/ml; normal level 23–300 ng/ml), D-dimer at 195 ng/ml (normal level 0–500 ng/ml) and no lymphopenia." (PMID 33195849, 2020). "Lymphopenia alone or elevated CRP levels without lymphopenia were not seen in fatal cases." (PMID 33089038, 2020). "The laboratory workup of the patient showed a high erythrocyte sedimentation rate (ESR), C-reactive protein (CRP), and white blood cell (WBC) count with no lymphopenia." (PMID 38978890, 2024). "In this study, CRP, LDH elevation, and lymphopenia were compared in groups with and without severe disease and found to comprise risk for severe disease." (PMID 35992514, 2022). "In blood tests, leukocytes were in at least normal range, but lymphocytopenia has not been observed, and inflammatory markers such as ESR and CRP increased." (PMID 35872680, 2022). "Upon admission, most of the patients also experienced lymphopenia (62.3%), eosinopenia (77.0%), and increased level of erythrocyte sedimentation rate (ESR) and C-reactive protein (CRP) (more than 90%), regardless of the disease severity." (PMID 35240947, 2022). "C-reactive protein (CRP) did not go up at the beginning, but a complete blood count (CBC) showed neutrophilia and lymphopenia along with 1% of eosinophils, which indicated the probable presence of viral infection." (PMID 35419241, 2022). "Laboratory testing on admission revealed that patients with lymphopenia had higher levels of CRP, IL-6, LDH, and creatinine compared to patients without lymphopenia." (PMID 35160150, 2022). "Even though lymphocytopenia and NLCR had good negative predictive values, CRP was found to be a superior marker in back-to-back analyses." (PMID 23506136, 2013). "Additionally, patients lacking α7nAchR levels presented with higher C-reactive protein (CRP) values, more pronounced lymphopenia, extended pulmonary lesions, and increased expression of the TNFα pathway." (PMID 36312286, 2022). "The complete blood count showed a high C-reactive protein with 45 mg/L, high level of ferritin (354 μg/L), LDH with 1342 UI/L and D-dimer, normal white blood cells with 6500 cells/mm3, normal fibrinogen, normal kidney function, without lymphopenia." (PMID 34512962, 2021).
coronary artery disease (1,118 papers, 2005 to 2026). "The other important biomarker, used for predicting coronary artery disease risk, is C-reactive protein (CRP) in the patient's serum." (PMID 40123746, 2025). "Low‐grade inflammation, detected through CRP, is widely recognized for its association with end‐organ damage and cardiovascular events, particularly coronary heart disease." (PMID 39526963, 2025). "Research indicates that an increase in DII scores correlates with elevated levels of interleukin-6 (IL-6), tumor necrosis factor-alpha (TNF-α), and C-reactive protein (CRP), as well as an increased risk of coronary heart disease development." (PMID 39796599, 2025). "This research aimed to explore the association of high-sensitivity C-reactive protein to albumin ratio (CAR) with death events in community-based patients with coronary heart disease (CHD)." (PMID 40435309, 2025). "Hs-CRP, a cardiovascular risk assessment marker used in patients with coronary artery disease, decreases with regular exercise." (PMID 40711080, 2025). "Multivariable analysis identified coronary artery disease (p = 0.023), multiorgan failure on admission (p = 0.035), and elevated CRP levels (p = 0.044) as independent risk factors for mortality at ICU admission." (PMID 41303238, 2025). "After adjusting for Framingham risk variables, individuals with CRP levels above 3.0 mg/L had a 58% higher risk of coronary artery disease compared to those with CRP levels below 1.0 mg/L." (PMID 40842496, 2025). "SI is not only a marker of disease activity (e.g., C-reactive protein [CRP]) but also a causative factor that accelerates lesion formation and progression in coronary artery disease (CAD), affecting both stable and unstable atheroma." (PMID 40722588, 2025). "The CRP/albumin ratio wasa risk factor in male patients, those aged ≥ 60 years old, and those witha BMI ≥ 25 kg/m2, coronary heart disease, or cerebralinfarction." (PMID 40622101, 2025). "Elevated CRP levels are associated with a higher risk of developing coronary heart disease and increased mortality rates." (PMID 39285289, 2024). "In turn, CRP and other proinflammatory markers have been associated with increased risk of hyperglycaemia and type 2 diabetes, as well as with ischemic heart disease (IHD) and CVD death." (PMID 38730445, 2024). "We also found that CRP ≥ 2 mg/L associates with increased risk of type 2 diabetes, and that CRP ≥ 2 mg/L and type 2 diabetes, individually and jointly, contribute to stepwise higher risk of ischemic heart disease and cardiovascular death." (PMID 38730445, 2024). "Inflammatory markers such as NLR (Neutrophil-lymphocyte ratio), PLR (Platelet-lymphocyte ratio) and CRP can be used to predict cardiovascular risk in patients with coronary artery disease." (PMID 38431565, 2024). "The hs-CRP value can be used as an indicator of cardiovascular risk, specifically as a marker for predicting the risk of developing coronary heart disease in healthy individuals." (PMID 39063602, 2024). "C reactive protein is an inflammatory marker that has been linked to the pathogenesis and prognosis in patients with coronary artery disease, congestive heart failure, and AF." (PMID 39274304, 2024). "A Mendelian Randomization study revealed that higher C-reactive protein was a causal risk factor for schizophrenia, coronary artery disease, and inflammatory bowel disease which are well-known risk factors for dementia." (PMID 38378514, 2024). "Current studies have already demonstrated that the combination of low HDL-C and elevated CRP levels is associated with adverse outcomes in patients with ischemic stroke, heart failure, and coronary artery disease." (PMID 39634189, 2024). "The second applied example sought to identify horizontally pleiotropic CRP-associated SNPs, when estimating the effect of CRP on coronary artery disease." (PMID 38421485, 2024).
coronary artery disease (continued). "Further, the decreased concentration of HDL in the BPH group together with their increased total cholesterol and C-reactive protein concentrations suggest that they were at risk of developing coronary heart disease." (PMID 39086866, 2024). "The predictive association between CRP and coronary heart disease has been extensively demonstrated." (PMID 38672153, 2024). "C-reactive protein (CRP) is a common inflammatory biomarker associated with the risk of coronary heart disease." (PMID 38398769, 2024). "Historically, keywords like “coronary-heart-disease” (2000–2014), “c-reactive protein” (2004–2012), and “cardiovascular risk factors” (2009–2015) commanded prolonged research attention." (PMID 38934020, 2024). "CRP can identify heart-transplants which are at high risk of ischemic events, being associated with the development, severity, and progression of coronary artery disease." (PMID 36826577, 2023). "It has been previously reported that in comparison to <1 mg/l hs-CRP levels, >3 mg/l was related to a 60% higher risk of coronary heart disease (CHD) incidence after adjustment of all Framingham risk variables (RR: 1.60; 95% CI: 1.43 to 1.78)." (PMID 37273333, 2023). "Patients have a higher risk of underlying ischemic heart disease with moderate or severe airflow obstruction and high circulating C-reactive protein (CRP), which indicates that this inflammatory marker has an effect on cardiac risk." (PMID 38034213, 2023). "Several proinflammatory cytokines, such as IL-6, IL-18, TNF-α and C-reactive protein, have been reported to be independently associated with the risk of coronary heart disease." (PMID 37308900, 2023). "Elevated levels of CRP >3 mg/Lwere associated with higher risk of ischemic heart disease and ischemiccerebrovascular disease." (PMID 39076864, 2023). "The study results showed that there was a positive relationship between C-reactive protein synthesis index (CRP) and the risk of coronary heart disease and mortality from cardiovascular disease." (PMID 37443056, 2023). "Studies in short-term exposure to ambient PM in young and elderly patients with coronary arterial disease (CAD) showed a significant association between CRP and elevated PM." (PMID 35886623, 2022). "These keywords included low grade inflammation (5643,0.01), cardiovascular risk factor (3865, 0), gene expression (3293, 0.01),coronary artery disease (3068, 0), CRP (2098, 0), acute myocardial infarction(1964, 0), and mortality (1404, 0)." (PMID 39077721, 2022). "Previous studies indicate that C-reactive protein (CRP) is elevated in individuals who are at risk of developing coronary artery disease or undergoing adverse cerebrovascular events." (PMID 36262245, 2022). "A few studies have also reported age, chronic kidney dysfunction, higher CRP levels, and coronary artery disease as risk factors associated with a poorer prognosis and higher mortality." (PMID 36362816, 2022). "Genetic associations with serum CRP and fibrinogen levels and two positive controls (rheumatoid arthritis and coronary heart disease)." (PMID 35747747, 2022). "Previous research only focused on the relationship between the combination of CRP and HbA1c with subsequent outcomes, such as carotid atherosclerosis progression, cardiovascular risk, severe coronary artery disease, and DM." (PMID 35252292, 2022). "As we know, HCY, TC, and LDL-C are independent risk factors for coronary heart disease, and CRP, a sensitive marker of chronic low-grade inflammation, is associated with an increased risk of incident coronary heart disease." (PMID 36354350, 2022). "High-sensitivity CRP is an acute phase reactant (specific inflammation marker) that can be used as a prognostic factor for coronary heart disease, risk assessment, and the evaluation of therapy response in CVD." (PMID 35204113, 2022).
coronary artery disease (continued). "Early meta-analysis in the last decade demonstrated that elevated C-reactive protein (CRP) levels were positively correlated with the risk of coronary artery disease (CAD), ischaemic stroke, and mortality in individuals without underlying vascular diseases." (PMID 35054989, 2022). "Among these patients with LVEF > 40% plus CRP tertile 3, statin use was associated with 46% reduced risk for mortality in those with ischemic heart disease (HR 0.54, 95% CI 0.31–0.97)." (PMID 36620625, 2022). "Increased circulating IL-6 levels are associated with coronary artery disease, promote vascular inflammation, and increase circulating CRP levels." (PMID 36012889, 2022). "Previous studies have shown that the combined effects of HbA1c and hs-CRP are associated with advanced subclinical carotid atherosclerosis progression, cardiovascular risks, and coronary artery diseases." (PMID 35252292, 2022). "Coronary artery disease was significantly associated with elevated CRP levels in this study, and serum LDL-C was also associated with elevated CRP, with statistically significant differences (P < 0.05)." (PMID 36418968, 2022). "It was also shown that, among patients with stable coronary artery disease, elevated CRP level increases the risk of myocardial infarction, while in patients with myocardial infarction, it contributes to an increased risk of complications and worse prognosis." (PMID 33407375, 2021). "The CRP level as a degree of inflammation is linked with the prognosis of coronary artery disease and shows a strong impact on the model, which is consistent with previous studies." (PMID 34647900, 2021). "The clinical implications of elevated hs-CRP have been investigated in relation to cardiovascular disease risk in particular and described as a predictor of coronary heart disease." (PMID 35010890, 2021). "Other studies looking at coronary artery disease and deep venous thrombosis have shown that CRP-level increases were associated with FPC formation." (PMID 33959088, 2021). "We believe that CRP, as a useful and easily available biomarker, can be used to improve the risk assessment and secondary prevention of coronary heart disease." (PMID 34900087, 2021). "Even the extent of coronary artery disease (categorized as 1‐ or 2‐vessel disease, 3‐vessel or left main disease, inconclusive angiographic findings) was associated with CRP (ln) in MI‐CAD when added as additional variable to model 2 (β = 0.041; p < .001)." (PMID 34032303, 2021). "Other studies reported that CRP was associated with coronary artery disease, suggesting a beneficial effect of lowering inflammation as well." (PMID 34386016, 2021). "IL6R rs4537545T* allele is also associated with C-reactive protein, allergic disease, rheumatoid arthritis and coronary artery disease." (PMID 33517400, 2021). "Growing evidence of CRP-reducing effects of statins indicates that this class of medications reduces the risk of cardiovascular events in patients with coronary artery disease." (PMID 34489618, 2021). "C-reactive protein (CRP) can help to refine the global risk assessment for coronary heart disease (CHD), particularly among persons who are at intermediate risk on the basis of traditional risk factors alone." (PMID 34947938, 2021). "One very small study in Tanzania found CRP levels were strongly associated with coronary heart disease." (PMID 33141863, 2020). "Chronically elevated CRP is linked with coronary artery disease however, elevated serum levels of CRP or SAA can also indicate other health conditions such as cancer." (PMID 32733818, 2020). "Pre-treatment CRP level was significantly associated with coronary heart disease (p < 0.0001), histology (p = 0.013), tumor size (p = 0.018), tumor stage (p = 0.002), and vascular invasion (p = 0.017)." (PMID 31936329, 2020).
coronary artery disease (continued). "The combination of high CRP and low cholesterol have traditionally been linked to increased risk of coronary artery disease, but studies have also found high co-morbidity between cardiovascular disease and depression." (PMID 32404908, 2020). "In turn, increased CRP is associated with a higher risk of coronary heart disease in metabolically preloaded people." (PMID 32326591, 2020). "The most common variants in HNF1A are rs1169288 (A/C, Ile27Leu), rs2464196 (G/A, Ser487Asn), and rs1169310 (C/T), which have been reported to be associated with the CRP level, coronary artery disease, and diabetic retinopathy." (PMID 31915469, 2019). "Elevated serum levels of CRP are associated with different chronic inflammatory diseases, including coronary heart disease, rheumatoid arthritis and cancer." (PMID 30858869, 2019). "Increased CRP associated with behavioral stress has been demonstrated in healthy men and patients with coronary artery disease." (PMID 31443228, 2019). "The FRISC study included 917 patients with unstable coronary artery disease and the investigators found that elevated CRP levels were strongly associated with the long-term risk of death from heart disease." (PMID 31399624, 2019). "They concluded that elevated levels of inflammatory markers, particularly CRP, indicate an increased risk of coronary disease." (PMID 31337127, 2019). "Conversely, high-sensitivity C-reactive protein, pulse wave analysis and heart rate variability were unrelated to prognosis at 5 years after risk modification and treatment of coronary disease." (PMID 30943979, 2019). "Given that CVD is a major cause of mortality in T2DM, CRP has been proven to be a better predictor for coronary heart disease than other inflammatory markers, such as tumor necrosis factor alpha (TNF-α) and IL-6." (PMID 31208420, 2019). "High levels of IL-6 and CRP were significantly associated with an increased risk of coronary disease in both sexes, while high levels of soluble TNF receptors were significantly associated only among women." (PMID 31337127, 2019). "An individual with a CRP level higher than 3 mg/L has an increased risk of coronary heart disease, and this risk increases in those with type 2 diabetes." (PMID 29706967, 2018). "The liverresponds to the inflammatory process by synthesizing acute-phase protein, CRP, whichis a known marker of coronary heart disease risk in ill patients." (PMID 29617504, 2018). "In this respect, the serum CRP concentration has close associations with the risk of coronary heart disease, ischemic stroke, and vascular mortality." (PMID 30254628, 2018). "Among inflammatory mediators, raised plasma levels of C-Reactive Protein (CRP) is associated with increased risk of coronary heart diseases." (PMID 30069429, 2018). "Higher CRP levels are also associated with worse cardiopulmonary exercise performance in patients with ischemic heart disease and systolic HF." (PMID 30619885, 2018). "CRP has also been shown to have significant prognostic and diagnostic value in other conditions, including coronary heart disease, MI and ischemic stroke." (PMID 28355230, 2017). "Other biomarkers of inflammation are associated with greater risk of coronary disease, and U.S. guidelines recommend that high-sensitivity C-reactive protein can be measured to inform decisions on cardiovascular risk management in uncertain cases." (PMID 28254179, 2017). "The elevated levels of the two inflammatory markers IL-10 and hs CRP are suggestive of potential coronary heart disease risk in the HIV infected patients." (PMID 29387269, 2017). "GWAS’s have related IL6R to immune diseases and associated traits, including coronary heart disease, pulmonary function, asthma, C-reactive protein, rheumatoid arthritis and IBD susceptibility." (PMID 28129359, 2017). "ARG1 regulated the C-reactive protein (CRP) levels whose high levels were risk factors of coronary heart disease." (PMID 28903366, 2017).